TOGARAM1 (TOG array regulator of axonemal microtubules 1)
Description:
Involved in ciliogenesis. It is required for appropriate acetylation and polyglutamylation of ciliary microtubules, and regulation of cilium length. Interacts with microtubules and promotes microtubule polymerization via its HEAT repeat domains, especially those in TOG region 2 and 4 (By similarity).
Synonyms: FAM179B; KIAA0423; Crescerin-1; crescerin; JBTS37
Tractability: PROTAC: ubiquitination databases record sites on it.
Gene: Protein-coding gene on chromosome 14 (44,962,190 to 45,074,431, forward strand). Ensembl gene ENSG00000198718.
Subcellular location: Cell projection, cilium; Cytoplasm, cytoskeleton; Cytoplasm, cytoskeleton, cilium axoneme
Subcellular location (Human Protein Atlas): Microtubules; Nuclear speckles; Primary cilium
Gene Ontology:
Molecular function: identical protein binding; protein binding; microtubule binding
Biological process: cilium assembly; axoneme assembly; microtubule cytoskeleton organization; non-motile cilium assembly; positive regulation of microtubule polymerization
Cellular component: axoneme; cilium; ciliary basal body; cytoplasmic microtubule; microtubule; cytoskeleton
Genetic constraint (gnomAD): Loss-of-function variants: 81 observed, 134.52 expected, observed/expected ratio (o/e) 0.6, 90% interval 0.5 to 0.72. The upper end of that interval is the gene's LOEUF score, 0.72, which puts it in group 2 of 6, group 1 being the genes least tolerant of losing a copy. Missense variants: 1,864 observed, 1,975.7 expected, observed/expected ratio (o/e) 0.94, 90% interval 0.91 to 0.98. Synonymous variants: 704 observed, 728.37 expected, observed/expected ratio (o/e) 0.97, 90% interval 0.91 to 1.03.
Homologues: Orthologues: chimpanzee TOGARAM1 (99% identical), macaque TOGARAM1 (97% identical), rabbit TOGARAM1 (91% identical), dog TOGARAM1 (90% identical), pig TOGARAM1 (90% identical), rat Togaram1 (88% identical), mouse Togaram1 (87% identical), guinea pig TOGARAM1 (78% identical), tropical clawed frog togaram1 (32% identical), Drosophila melanogaster chb (10% identical), Caenorhabditis elegans cls-1 (7% identical), Caenorhabditis elegans cls-3 (6% identical), and 1 more. Paralogues in human: TOGARAM2 (19% identical), CLASP2 (14% identical), CLASP1 (14% identical).
Diseases named in the same sentence as TOGARAM1 in open-access papers:
TOGARAM1 is named in the same sentence as 9 diseases in open-access papers, as found by Europe PMC text mining. Sharing a sentence is not in itself a finding about the gene and the disease. The quoted sentences say what the papers report.
ciliopathies (4 papers, 2023 to 2025). "In addition to the CPLANE genes, our search uncovered a number of additional ciliopathy genes associated with multi-systemic, brain, kidney, and eye ciliopathies (Cep135, Innp5e, Pex6, Togaram1)." (PMID 36737727, 2023). "Among 8 probands, we identified 12 variants in 7 genes associated with ciliopathies including Joubert syndrome (KIAA0586, ARMC4, BBS1, CEP83, ARMC9, TOGARAM1, WDR5)." (PMID 38585811, 2024). "Here we reconstituted in vitro the individual and collective activities of the ciliary tip module proteins CEP104, CSPP1, TOGARAM1, ARMC9 and CCDC66, which interact with each other and with microtubules and, when mutated in humans, cause ciliopathies such as Joubert syndrome." (PMID 39856351, 2025). "Further, polyglutamylation was described to affect the JS-related ARMC9/TOGARAM1 protein complex, indicating that this PTM is closely related to this ciliopathy." (PMID 36674791, 2023).
Joubert syndrome (4 papers, 2021 to 2025). Joubert syndrome (JS) is characterized by congenital malformation of the brainstem and agenesis or hypoplasia of the cerebellar vermis leading to an abnormal respiratory pattern, nystagmus, hypotonia, ataxia, and delay in achieving motor milestones. "Moreover, CCDC66 is part of a ciliary tip module that includes other MAPs such as CEP104, CSPP1, TOGARAM1 and ARMC9, which are mutated in the Joubert syndrome." (PMID 40729374, 2025). "Moreover, the interactome contained components of the CCDC66-linked Joubert syndrome module, such as ARMC9, TOGARAM1, CEP104 and CSPP1, known for their roles in cilium length regulation." (PMID 40729374, 2025). "Even though these interacting proteins are not directly linked to ciliary disassembly, it is interesting to see that not CKAP5, but another TOG-domain protein, TOGARAM1, is involved in MT organization in cilia and that recent studies have linked TOGARAM1 to Joubert syndrome." (PMID 33860332, 2021).
cancer (3 papers, 2015 to 2021). A tumor composed of atypical neoplastic, often pleomorphic cells that invade other tissues. "The regulation of TOGARAM1 expression by DNA methylation and its role in cancer have not yet been reported." (PMID 34184409, 2021).
TOGARAM1 also shares sentences with these, for which no sentence is quoted: esophageal adenocarcinoma (2 papers); ciliary dyskinesia (1); hemorrhagic disease (1); hepatocellular carcinoma (1); metabolic disease (1); multiple myeloma (1).